GAS2L1 (growth arrest specific 2 like 1)
Description:
Involved in the cross-linking of microtubules and microfilaments. Regulates microtubule dynamics and stability by interacting with microtubule plus-end tracking proteins, such as MAPRE1, to regulate microtubule growth along actin stress fibers.
Synonyms: GAR22
Tractability: Antibody: the Human Protein Atlas places it where antibodies can reach. PROTAC: ubiquitination databases record sites on it.
Gene: Protein-coding gene on chromosome 22 (29,306,394 to 29,312,787, forward strand). Ensembl gene ENSG00000185340.
Subcellular location: Cytoplasm, cytoskeleton; Cytoplasm, cytoskeleton, stress fiber
Subcellular location (Human Protein Atlas): Plasma membrane; Cell Junctions
Gene Ontology:
Molecular function: protein binding; actin filament binding; cytoskeletal anchor activity; microtubule binding
Biological process: microtubule bundle formation; protein localization to microtubule plus-end; regulation of microtubule polymerization or depolymerization; actin crosslink formation; cellular response to starvation; negative regulation of microtubule depolymerization
Cellular component: actin filament; microtubule plus-end; cytoplasm; stress fiber; cytoskeleton
Genetic constraint (gnomAD): Loss-of-function variants: 21 observed, 28.97 expected, observed/expected ratio (o/e) 0.72, 90% interval 0.51 to 1.04. The upper end of that interval is the gene's LOEUF score, 1.04, which puts it in group 4 of 6, group 1 being the genes least tolerant of losing a copy. Missense variants: 916 observed, 822.17 expected, observed/expected ratio (o/e) 1.11, 90% interval 1.05 to 1.18. Synonymous variants: 395 observed, 342.67 expected, observed/expected ratio (o/e) 1.15, 90% interval 1.06 to 1.25.
Homologues: Orthologues: chimpanzee GAS2L1 (99% identical), macaque GAS2L1 (98% identical), dog GAS2L1 (90% identical), pig GAS2L1 (90% identical), guinea pig GAS2L1 (88% identical), mouse Gas2l1 (87% identical), rat Gas2l1 (86% identical), tropical clawed frog gas2l1 (45% identical), zebrafish gas2l1 (44% identical), Drosophila melanogaster pigs (32% identical). Paralogues in human: GAS2 (17% identical), MICALL2 (13% identical), MICALL1 (12% identical), EHBP1 (11% identical), ASPM (10% identical), EHBP1L1 (9% identical), SMTNL1 (4% identical).
Diseases named in the same sentence as GAS2L1 in open-access papers:
GAS2L1 is named in the same sentence as 11 diseases in open-access papers, as found by Europe PMC text mining. Sharing a sentence is not in itself a finding about the gene and the disease. The quoted sentences say what the papers report.
pancreatic cancer (4 papers, 2020 to 2025). "A 2023 SCS study detected overexpression of GAS2L1 and EPCAM in circulating tumor cells and highlighted the potential of GAS2L1 as a novel biomarker for the diagnosis of pancreatic cancer." (PMID 41340965, 2025). "Furthermore, pancreatic cancer patients with overexpression of GAS2L1 have an unfavorable prognostic outcome." (PMID 33333841, 2020). "GAS2L1 is thus proposed as a novel biomarker of pancreatic cancer CTCs." (PMID 33333841, 2020). "For instance, analysis of early-stage pancreatic cancer samples via single-cell sequencing has identified specific overexpression of genes such as CLIC4 and GAS2L1 in circulating tumor cells." (PMID 41463034, 2025). "Therefore, the overexpression of GAS2L1 in pancreatic CTCs and its utility in combination with EPCAM as a cell surface marker represent a promising approach for detecting and isolating pancreatic CTCs, and highlights the potential of GAS2L1 as a novel biomarker for pancreatic cancer." (PMID 37720505, 2023). "The combination of EPCAM/GAS2L1 surface protein stainings may increase the detection rate and comprehensiveness of CTC studies in pancreatic cancer without limiting the availability of the isolated CTCs for downstream analyses." (PMID 33333841, 2020).
acute myeloid leukaemia (1 paper, 2021). "GAS2L1 was markedly diminished in acute myeloid leukaemia, and the mutation of GAS2L1 may be associated with the neoplastic transformation of meningioma." (PMID 33103301, 2021).
COVID-19 (1 paper, 2025). A disease caused by infection with severe acute respiratory syndrome coronavirus 2. "The results demonstrated that SLC9A6 and GAS2L1 were also significantly differentially expressed in patients diagnosed with COVID-19." (PMID 39965013, 2025). "Similarly, for COVID-19, BCL6, PRR11, and GAS2L1 showed significant positive correlations with hypoxia, cholesterol homeostasis, xenobiotic metabolism, and glycolysis, and negative correlations with oxidative phosphorylation." (PMID 39965013, 2025).
glioma (1 paper, 2021). A benign or malignant brain and spinal cord tumor that arises from glial cells (astrocytes, oligodendrocytes, ependymal cells). "We also analyzed the mutation status of GAS2, GAS2L1, GAS2L2, and GAS2L3 in the glioma samples of TCGA‐LGG/GBM or CGGA‐WEseq_286 project, respectively." (PMID 33713047, 2021). "Compared with GAS2, GAS2L1, and GAS2L2, there is a stronger correlation between GAS2L3 gene expression and glioma prognosis." (PMID 33713047, 2021). "In summary, compared with GAS2, GAS2L1, and GAS2L2, there is a stronger correlation between GAS2L3 gene expression and glioma prognosis." (PMID 33713047, 2021). "Herein, we first comprehensively explored the potential correlation between growth‐arrest‐specific two family genes (GAS2, GAS2L1, GAS2L2, GAS2L3) and gliomas by bioinformatics analysis and cellular experiments." (PMID 33713047, 2021). "Therefore, our findings did not provide strong evidence regarding the correlation between the expression of GAS2, GAS2L1, and GAS2L2 and the clinical prognosis of glioma cases." (PMID 33713047, 2021). "Regarding the GAS2L1 gene, we observed a negative correlation between the gene expression and the WHO grading or the poorer clinical OS prognosis (array_301, seq_325) of glioma cases within the CGGA database." (PMID 33713047, 2021). "Apart from GAS2L3, we did not observe the strong evidence supporting the significant expression difference of the GAS2, GAS2L1, and GAS2L2 genes between glioma cases and negative controls." (PMID 33713047, 2021).
pancreatic adenocarcinoma (1 paper, 2020). "GAS2L1 was significantly overexpressed (p < 0.001) in pancreatic adenocarcinoma as compared to matched normal tissue and the normal pancreatic data from the Broad Genotype-Tissue Expression (GTEx) portal." (PMID 33333841, 2020). "We further investigated whether the expression levels of GAS2L1 correlated with clinical prognosis (OS and RFS) in the pancreatic adenocarcinoma cohort of TCGA." (PMID 33333841, 2020).
schizophrenia (1 paper, 2017). A major psychotic disorder characterized by abnormalities in the perception or expression of reality. "GAS2L1 is a susceptibility locus for schizophrenia, and SASH1 gene expression was affected by a history of substance dependence/abuse." (PMID 29321746, 2017).
tumor (6 papers, 2020 to 2025). "In studies aiming to quantify all tumor-derived cells in the bloodstream, GAS2L1 should therefore be combined with other markers such as EPCAM." (PMID 33333841, 2020). "However, this hypothesis is limited by the missing correlation between GAS2L1 and OS in the clinical dataset, as well as the comparison between GAS2L1 expression in tumor tissue and CTCs." (PMID 33333841, 2020). "In this study, we found that GAS2L1 and GAS2L3 were distinctly upregulated in HCC specimens compared to non-tumor specimens." (PMID 38858234, 2024). "In 1996, GAS2L1, also called GAS2‐related protein on chromosome 22 (GAR22), was identified as a tumour suppressor gene within the chromosome 22q12 region." (PMID 33103301, 2021). "Additionally, more cell, animal and clinical sample‐based investigations are needed to further explore the potential role or clinical benefits of GAS2L1, GAS2L2 and GAS2L3 in the aetiology and pathogenesis of relevant diseases, such as tumours." (PMID 33103301, 2021).
cancer (3 papers, 2020 to 2024). A tumor composed of atypical neoplastic, often pleomorphic cells that invade other tissues. "The role of Gas2l1 (growth arrest specific 2 like 1) in cancer is largely unknown, and even more so in CTCs." (PMID 33333841, 2020). "Pan-cancer assays indicated that GAS2L1 and GAS2L3 were highly expressed in most cancers." (PMID 38858234, 2024).
GAS2L1 also shares sentences with these, for which no sentence is quoted: glioblastoma (1 paper); hepatocellular carcinoma (1); meningioma (1).